SNAI2 (snail family transcriptional repressor 2)
Diseases named in the same sentence as SNAI2 in open-access papers (continued):
Sharing a sentence is not in itself a finding about the gene and the disease.
cancer (continued). "Future studies will define if cancer maintaining cells (or cancer stem cells) keep constitutively active part of the original genetic programme controlled by Snai2 in MEFs in response to DNA damage." (PMID 18182996, 2008). "The function of Snai2 in response to DNA damage seems to be critical for its function in normal development and cancer." (PMID 18182996, 2008). "The analysis of the Snai2-expressing mice identified that ‘uncontrolled’ Snai2 expression induces cancer in mice." (PMID 18182996, 2008). "The upregulation of multiple lineage plasticity genes, including basal (Trp63, Krt5 and Krt14), metastasis (Snai2, Tgfb1 and L1cam), and stemness (Sox2, Mecom and Sox6) markers was induced by LKB1 loss, further supporting the enhanced cancer cell state plasticity by LKB1 loss." (PMID 39743630, 2025). "Given that M2 macrophages are known to induce epithelial‐mesenchymal transformation (EMT) in cancer cells, we explored the correlation between VSIG4 and several biomarkers associated with EMT processes (MMP9, SNAI1, SNAI2, VIM, TWIST1, TWIST2, CDH1, CDH2) in CRC through the TIMER2.0 website." (PMID 40405491, 2025). "Our observations suggested that the increased expression of BIM and BMF that results from SNAI2 knockdown may enhance apoptosis in TPM cancer cells treated with MEK1/2 and HDAC inhibitors." (PMID 40560846, 2025). "Snail family transcriptional repressor 2 (Snail2) and yes-associated protein 1 (YAP1) are known oncogenes that are up-regulated in cancer, circRNAPCNX serves as a sponge for miR-506 and inhibits the anti-cancer activity of miR-506 via the circRNAPCNX-miR-506-Snail2/YAP axis in HCC." (PMID 40248198, 2025). "To further investigate the regulatory potential of SNAI2 in TPM cancer cell survival, we tested whether its expression limited the efficacy of MEKi and HDACi in inducing cell death." (PMID 40560846, 2025). "SNAI2 can regulate cancer cell DNA damage responses, suggesting that SNAI2 may suppress apoptosis by enhancing DNA repair." (PMID 40560846, 2025). "As we showed that BIM is important for regulating cell death in TPM cancers, we considered that SNAI2 may also play a role in regulating BIM." (PMID 40560846, 2025). "SNAI2 is a transcription factor known for its role in epithelial-to-mesenchymal transition (EMT), which is often associated with increased invasiveness and resistance to apoptosis in cancer cells." (PMID 40560846, 2025). "We integrated analyzed the function of P4HA3 among 33 types of cancers, and found that P4HA3 was associated with proliferation markers (PCNA and MKI67), EMT markers (VIM, TWIST1, SNAI1, SNAI2, FN1 and CDH2), extracellular matrix (ECM) markers (MMP9, MMP7, MMP2 and MMP14)." (PMID 39504328, 2024). "Myosin-1b (MYO1B) promotes cancer by targeting HIF1a and SNAI2/cyclinD160,61." (PMID 38291075, 2024). "Mechanistically, we found that GNPNAT1 could promote cancer cell metastasis by stabilizing Snai2 in LUAD." (PMID 39062049, 2024). "Studies have shown that Snai2 expression correlates with poor prognosis and may promote cancer cell metastasis in LUAD." (PMID 39062049, 2024). "Therefore, SNAI2 plays an indispensable role in a variety of tumors, which further increases our interest in pan-cancer analysis." (PMID 37251370, 2023). "Importantly, our findings have wider implications against other cancers with aberrant upstream receptor activation, as SNAI2 can work together with oncogenes such as RAS and ERBB2 to enhance tumorigenicity." (PMID 37228489, 2023). "We explored different aspects of SNAI2 in this pan-cancer study and discovered that SNAI2 could be a powerful biomarker across cancer types, particularly in the era of immunotherapy." (PMID 37251370, 2023). "Moreover, SNAI2 was previously reported to play a mediator role in regulating the stem-like phenotype in several types of cancer." (PMID 36674577, 2023). "Firstly, we analyzed the SNAI2 expression in various cancers and cancer cell lines." (PMID 37251370, 2023).
cancer (continued). "The single-cell analysis of SNAI2 in single-cell datasets of cancer samples was analyzed." (PMID 37251370, 2023). "The prognostic significance of SNAI2 in various cancers was evaluated." (PMID 37251370, 2023). "Besides, the correlation analysis of SNAI2 and immune regulators in pan-cancer suggested that SNAI2 expression was correlated with many immune regulator gene expressions, especially in ACC, COAD, KICH, and READ." (PMID 37251370, 2023). "In addition, the analysis of genetic alterations in a pan-cancer cohort showed that the frequency of alterations in the SNAI2 gene was at a maximum of 15%." (PMID 37251370, 2023). "Previous studies have shown that SNAI2 can induce the invasiveness of cancer cells; predictably, MMP12 might be involved in LUSC metastasis as a downstream gene of SNAI2, and this proposition was reinforced by ChIP-Seq data in the Cistrome Data Browser." (PMID 37601247, 2023). "As a result, our findings could help researchers learn more about the potential function of SNAI2 in cancer immunotherapy." (PMID 37251370, 2023). "In conclusion, these findings showed that SNAI2 was abnormally expressed in a variety of malignancies, and could be a new cancer biomarker." (PMID 37251370, 2023). "SNAI2 was positively associated with the infiltration levels of CAF, Endo, Neutrophil, Monocyte, Macrophage, Gran, and HSC, and negatively associated with the infiltration levels of B cell plasma in most TCGA cancers, especially in BRCA, HNSC, TGCT." (PMID 37251370, 2023). "Elevated expression of SNAI1 and SNAI2 have been observed in a variety of cancer types and correlate with increased risks of metastasis and postoperative relapse, predicting poor prognosis for the survival in cancer patients." (PMID 37596321, 2023). "Therefore, in this study, our systematic and detailed analysis of SNAI2 in pan-cancer provides a broad elaboration of cancer biology by using The Cancer Genome Atlas (TCGA), Cancer Cell Line Encyclopedia (CCLE), and Genotype-Tissue Expression (GTEx) databases." (PMID 37251370, 2023). "Further investigation should focus on the function of the SNAI2 protein in cancer cells." (PMID 37251370, 2023). "We also conducted a clinical sample test with PAAD samples, and the results of western blot and qRT-PCR analyses indicated that the expression of SNAI2 in the PAAD tissues was remarkably higher than that in normal tissues adjacent to cancer, which was also consistent with the database results." (PMID 37251370, 2023). "In previous studies, EMT has been significantly confirmed to be related to the occurrence, metastasis, and drug resistance of cancers, suggesting that SNAI2 might play an indispensable part in the oncogenesis and development of cancers by enrolling in EMT." (PMID 37251370, 2023). "Therefore, SNAI2 had a prognostic role in predicting the prognosis of cancers, but the roles were complicated and multifaceted across cancers." (PMID 37251370, 2023). "SNAI2 is well known as an EMT regulator in various carcinomas." (PMID 36674577, 2023). "In ccRCC, by facilitates the EMT, SNAI2 promotes cancer cell migration and invasion." (PMID 36338978, 2022). "Importantly, SNAI2 expression levels in part determine sensitivity to the cancer drugs dasatinib and panobinostat." (PMID 34792282, 2022). "Additionally, the overall survival analysis based on the TCGA data showed that ELF3-AS1 and SNAI2 possessed opposite prognoses in pan-cancer." (PMID 36457025, 2022). "In addition, microenvironmental sources of TGF-β contribute to the aggressive and metastatic nature of TNBC by enhancing SNAI2’s activity to further increase the plasticity of progenitors and subsequent numbers of invasive mesenchymal-like cancer cells." (PMID 36376460, 2022). "Hence, we analyzed TCGA expression data from 32 cancer types (∼9,000 patient samples) to identify LncRNAs associated with EMT markers, VIM, FN1, SNAI1, SNAI2, and CDH1 (and material and method)." (PMID 36120580, 2022).
cancer (continued). "Importantly, in most studies Vimentin and the EMT TFs were expressed at very low levels in the cancer cells and much more highly in CAFs, with the notable exception of SNAI2 in HNSCC." (PMID 33972543, 2021). "In addition to serving as a marker gene for NC specification and migration, Snai2 also functions to promote cell survival and control stem cell properties in cancer cells." (PMID 34977877, 2021). "Moreover, the structural homolog of LOXL1, LOX, transcriptionally regulates SNAI2 expression by transactivating the SNAI2 promoter in human cancer cells." (PMID 33095806, 2020). "Therefore, markers of EMT, such as vimentin, FN1, twist family bHLH transcription factor 1 (TWIST1), snail family transcriptional repressor 1 (SNAI1) and 2 (SNAI2, best known as SLUG) can be used to detect cancer dormancy." (PMID 33193295, 2020). "Thus, our results revealed that miR-222-3p was directly inhibited at the transcriptional level by SNAI2, which is a key transcription factor involved in the progression of many cancers." (PMID 32483426, 2020). "Many miRNAs target SNAI2 and regulate the metastasis of cancer." (PMID 31749661, 2019). "Similar processes could be expected in cancer cells in which high levels of SNAI2 result in more intensive binding of SNAI2 to the genomic targets, determining the differentiation status of epithelial cells." (PMID 30189837, 2018). "However, our results indicate the other possible role of the SNAI2 gene in BC, which is the de-differentiation of cancer cells." (PMID 30189837, 2018). "A mesenchymal phenotype, characterised by low expression of E-cadherin (CDH1), high expression of vimentin (VIM) and high expression of EMT-inducing transcription factors, such as TWIST1, ZEB1, SNAI1 and SNAI2 moreover correlates with the expression of cancer stem cell markers CD44 and CD90." (PMID 29299154, 2017). "These tumorigenic properties of MALAT1 were mediated by its ability to decoy miR-1 and, consequently, increase the expression of miR-1 target, SNAI2 (snail family transcriptional repressor 2), also named Slug, an oncogene involved in regulation of cancer cell invasion." (PMID 29147648, 2017). "Interestingly, SNAI2 cooperates with PRC2 to suppress the expression of E-Cadherin in cancer cells and during embryonic development." (PMID 26771648, 2016). "So it remains largely unknown the roles of endogenous SNAI2 in different malignant tumor under diverse circumstances." (PMID 27760172, 2016). "Suppression of SNAI2 suffices to up-regulate several cancer stem genes." (PMID 27760172, 2016). "SNAI2 expression is down-regulated in some of the pulmonary metastatic advanced carcinomas." (PMID 27760172, 2016). "Above all, our study shows that SNAI2 may condition prostate carcinogenesis as an up-stream regulator of multiple cancer progression pathways governed by pluripotency-, neuroendocrine- or metastasization-related gene." (PMID 25686823, 2015). "In post-natal life, the SNAI2 gene is widely expressed in adult human tissues, including the prostate, while its amplification or interaction with specific oncogenes have been demonstrated in a wide spectrum of human cancers." (PMID 25686823, 2015). "As regulators of invasiveness, TWIST1 and SNAI2 are potential targets for therapeutic modulation, a proposition further supported by their known functions to promote cell survival and treatment resistance in other cancer types." (PMID 20646316, 2010). "The implication of SNAI2 in human cancer seems to be wider than initially expected." (PMID 18182996, 2008). "The emerging model suggests that targeting the Snai2-mediated arm could effectively increase the radiosensitivity of Snai2-dependent cancers." (PMID 18182996, 2008). "Therefore, we believed that SNAI2 could be a robust immunotherapy biomarker for cancers, and it possessed the strong potential to be applied in clinical cancer treatment." (PMID 37251370, 2023). "Also, SNAI2 exhibits prognosis predictive ability in various cancers." (PMID 37251370, 2023).
cancer (continued). "And USP5 could regulate the stability of many tumorigenesis‐associated proteins, such as forkhead box M1 (FoxM1), MAF bZIP transcription factor (c‐Maf), Tu translation elongation factor, mitochondrial, and snail family transcriptional repressor 2 (SNAI2) to promote the cancer progression." (PMID 37492786, 2023). "Therefore, a therapeutic intervention that interrupts the functional SNAI2/miR-222-3p/PDCD10 axis might provide a promising strategy to treat EOC cancer." (PMID 32483426, 2020). "During EMT, cancer cells lose their cell-to-cell attachment by decreasing E-cadherin expression, due to hypermethylation of the promoter region or transcriptional repression caused by Zinc finger E-box-binding homeobox 1 (ZEB1), ZEB2, Snail, Slug (also known as SNAI2), and TWIST." (PMID 29758011, 2018). "However, the roles of endogenous SNAI2 remain controversial in different types of malignant tumors." (PMID 27760172, 2016). "Module 5 contains known EMT inducers ZEB1, SNAI2, and TCF4 (E2.2), as well as multiple other genes known to be important in focal adhesion, extracellular matrix interaction, extracellular matrix organization, and markers of cancer-associated fibroblasts (PDGFRB, PDGFRA)." (PMID 27287041, 2016). "Selective SNAI2 expression in cancer cell clusters at the invasion front, or in NED areas of poorly differentiated PCa may endow these cells with stemness and/or neuroendocrine traits and migration/invasion property, thus promoting their self-renewal and metastatic capabilities." (PMID 25686823, 2015). "Transcription factor Slug/SNAI2 (snail homolog 2) plays a key role in the induction of the epithelial mesenchymal transition in cancer cells; however, whether the overexpression of Slug mediates the malignant phenotype and alters drug sensitivity in lung cancer cells remains largely unclear." (PMID 23634282, 2013). "The epithelial-mesenchymal transition (EMT) drives cancer progression, regulated by transcription factors (TFs) such as SNAI1, SNAI2, ZEB1, ZEB2, and TWIST." (PMID 41481650, 2026). "CDH2, ZEB2, SNAI2, and SNAI1 are important regulatory genes that increase the motility and invasion capacity of cancer cells." (PMID 41179704, 2025). "In OC, miR-506 suppresses SNAI2-mediated EMT, thereby restricting the acquisition of stem-like properties in cancer cells and enhancing their response to chemotherapy and radiotherapy." (PMID 40248198, 2025). "Cytoskeletal regulators (MYL9, TAGLN) and transcription factors (SNAI2) promote EMT and cancer stemness, while PMEPA1, IL6, IL8, IGFBP3, INHBA, and VEGFA contribute to proliferation, angiogenesis, and immune modulation." (PMID 41009714, 2025). "SNAI2 is a snail family transcriptional repressor that is involved in regulating the epithelial-to-mesenchymal transition (EMT) and the migration of cancer cells." (PMID 40110710, 2025). "miR-506 enhances the expression of E-cadherin, reduces the expression of SNAI2 and VIM, and inhibits cancer cell migration and invasion." (PMID 40248198, 2025). "Given the well-documented association between elevated SNAI2 levels and mesenchymal phenotypes, this suggested a compelling link between SNAI2 expression and the aggressive phenotype observed in TPM cancers." (PMID 40560846, 2025). "There were no changes in the expression of the transcription factors TWIST, SNAI1 (SNAIL), and SNAI2 (SLUG), master regulatory factors for organogenesis and wound healing tightly involved in the EMT of cancer cells." (PMID 38399969, 2024). "Due to their central role in EMT and extensive studies in cancer, ZEB1, ZEB2, SNAI1, SNAI2 and TWIST1 are considered as the core EMT-TFs." (PMID 39164745, 2024). "Stem cell-related genes such as SOX2, NANOG, KLF4, OCT4, SNAI2, SNAI1, SOX9, and others are significant promoters of stemness and contribute to increased metastasis in various cancer types." (PMID 38920995, 2024).
cancer (continued). "In cancer cells, KLF4 is suppressed, and YAP promotes snail family transcriptional repressor 2 (SNAI2) expression, which is involved in downregulating KLF4 expression." (PMID 39684613, 2024). "However, the significance of SNAI2 in human pan-cancer is still largely unknown." (PMID 37251370, 2023). "For example, multiple studies have reported that EMT drivers, such as SNAI2, ZEB1 and Twist1, play critical roles in cancer cell stemness in cancers." (PMID 36808651, 2023). "Meanwhile, the critical transcription factors, including TWIST1, TWIST2, ZEB1, ZEB2, SNAI1 and SNAI2, participate in the EMT process, leading to cancer cell migration and invasion." (PMID 37794509, 2023). "It was reported that SNAI2 plays a crucial role in SDF1 production by CAFs in both mice and humans, as well as in establishing the heterocellular signaling loop between cancer cells and fibroblasts." (PMID 37251370, 2023). "In turn, these pathways utilise a variety of transcription factors (EMT-TFs) such as SNAI1, SLUG/SNAI2, TCF3, TWIST1/2 and ZEB1/2, to alter expression of tissue and cancer-specific proteins." (PMID 37832352, 2023). "SNAI2 expression was also found to have a high correlation with the DNA mismatch repair (MMR) genes and DNA methylation in many cancers." (PMID 37251370, 2023). "Further, the siRNA reduction of IPO5 in TCam-2 cells lowered levels of SNAI2, a BMP4-regulated gene expressed in TGCTs known to function in cancer metastasis." (PMID 37048077, 2023). "VEGFA promotes cancer cell renewal, cell migration, invasion and metastasis through induction of SOX-2, which in turn activates SNAI2, an EMT transcription factor." (PMID 37173939, 2023). "We tested protein expression for ZEB1 and the mesenchymal cancer cell proteins MMP2, SNAI2, and CD44 due to their upregulation in GBM vs. normal tissue." (PMID 37761927, 2023). "The mouse homolog of Snai2 was subsequently cloned from mouse cDNA using chicken Snai2 oligos, and found to initiate EMT when ectopically expressed in a rat carcinoma cell line." (PMID 37600794, 2023). "Several transcriptional repressors, including Snail (SNAI1), Slug (SNAI2) and ZEB family, play a key role of EMT in cancer and development." (PMID 35426224, 2022). "We used pan-cancer expression data to find 14-LncRNAs that had a high correlation with the EMT markers VIM, CDH1, FN1, SNAI1, and SNAI2." (PMID 36120580, 2022). "EMT is a complex program that incorporates many pathways mediated by the transcription factors SNAIL, SNAI2 (or SLUG), TWIST, and ZEB, whose differential expression in cancer was shown to lead to EMT." (PMID 36232784, 2022). "CHD1L also contributes to stemness in pluripotent cells, it regulates pluripotency, differentiation and invasiveness of cancer cells; furthermore, inhibition of CHD1L was reported to down-regulate SNAI2 expression." (PMID 35864202, 2022). "TOX high mobility group box family member 3-like (TOX3) in the spleen has been shown to inhibit the proliferation and migration of cancer cells by transcriptional regulation of SNAI1 and SNAI2 to prevent disruption of the epithelial cell layer." (PMID 34135900, 2021). "Because EMT requires both sufficient BACH1 and SNAI2 for the repression of epithelial genes, such a GRN precludes spontaneous EMT in cancer cells: EMT ensues only when enough BACH1 and SANI2 have accumulated within cells." (PMID 34339740, 2021). "Transcription factors known to regulate EMT include ZEB1, ZEB2, SNAI1 (SNAIL), SNAI2 (SLUG), and TWIST1 and have been suggested to promote cancer progression, including metastasis." (PMID 34339740, 2021). "Firstly, SNAI2 is highly expressed in FN-RMS tumors compared to normal muscle and the majority of other cancers." (PMID 33420019, 2021). "Members of the SNAI family, including Snail (SNAI1), Slug (SNAI2), and Smuc (SNAI3), are considered as indicators of the malignancy of cancer." (PMID 34876945, 2021).